ADAM12 (ADAM metallopeptidase domain 12)
Diseases named in the same sentence as ADAM12 in open-access papers (continued):
Sharing a sentence is not in itself a finding about the gene and the disease.
tumor (continued). "Recently, irradiation-induced upregulation of ADAM12 was observed in mouse and human colon cancer cells, as well as rectal cancer patient tumour tissues." (PMID 40427200, 2025). "In hepatocellular carcinoma, clinical dataset analyses revealed a strong correlation between high ADAM12 expression and an advanced tumour stage." (PMID 40427200, 2025). "For example, ADAM12 promotes efferocytosis and polarizes macrophages toward an immunosuppressive M2 phenotype in a tumor microenvironment via an AXL-dependent mechanism involving Gas6 secretion." (PMID 41181101, 2025). "ADAM12 was expressed by all primary tumours and was detectable in the cytosol of tumour cells in the mesenteric metastases." (PMID 40998421, 2025). "The radiogenomic features of ADAM12 expression in ccRCC include primary tumor size, ill-defined margins, tumor necrosis, and collecting system invasion." (PMID 40282346, 2025). "Disintegrin metalloprotease, ADAM12, expressed in CAFs and tumor cells, is reactivated in fibroblasts during fibrogenesis in desmoplasia." (PMID 40230862, 2025). "Vaccination against ADAM12 depletes CAFs and delays tumor growth, by reducing ADAM12+ CAFs, and decreases deposition of ECM." (PMID 40230862, 2025). "RNA‐seq demonstrated that, among the most altered genes involved in the tumor–stroma crosstalk, are ADAM12 and CYP1B1, which were proven to be key promoters of RCC tumorigenesis." (PMID 39806854, 2025). "Another metalloprotease was found to be overexpressed in CAFs, ADAM12, a regulator of cell–matrix and cell–cell interactions; it has been involved in tumour progression." (PMID 38339377, 2024). "Analysis of gene expression data in claudin-low TNBCs from the METABRIC patient cohort reveals significant inverse correlations between ADAM12 and gene expression profiles of various anti-tumor immune cell populations." (PMID 38317965, 2024). "The ADAM12 vaccine induces a redistribution of CD8+ T cells within the tumor and cytotoxic responses against ADAM12+ cells." (PMID 39478152, 2024). "This study validated the efficacy of a vaccine against ADAM12+ cells via improved CD8+ cytotoxic T cell response in two different PDAC tumor mouse models." (PMID 39478152, 2024). "ADAM12 vaccination further promoted infiltration and a favorable redistribution of different T cell subtypes within the tumor tissue." (PMID 39478152, 2024). "On the other hand, the expression of the ADAM12 gene was high in tumor tissue compared to normal tissue, which contrasted with the findings regarding protein expression." (PMID 39596804, 2024). "This further underscores the regulatory influence of slow-cycling ADAM12+MSCs on the tumor microenvironment through the TGF-β signaling pathway." (PMID 38779660, 2024). "The expression of ADAM12 has been reported to be upregulated in various tumor cells and is an emerging prognostic biomarker for cancer." (PMID 37935791, 2024). "The specific knockout of TGF-βR2 in ADAM12+ cells significantly impeded tumor growth while enhancing T-cell infiltration and promoting vascular normalization." (PMID 38779660, 2024). "The significant role of ADAM12 in the promotion of the angiogenesis process was indicated in the mice model and the tumour cell lines." (PMID 38773369, 2024). "The overexpression of ADAM12 in MCF7 cells resulted in a significantly higher tumor burden compared with the control MCF7-A12 delta cyt + Dox mice after 2–3 weeks." (PMID 38892056, 2024). "Using both subcutaneous and orthotopic PDAC mouse models, we show that vaccination against ADAM12 depletes CAFs and delays tumor growth." (PMID 39478152, 2024). "The positive effect of ADAM12 on tumor growth was further confirmed in a subcutaneous xenograft tumor mouse model." (PMID 36717944, 2023). "We found that abnormally high ADAM12 expression promoted tumor growth and metastasis by enhancing cell proliferation, migration, and invasion." (PMID 36717944, 2023).
tumor (continued). "To investigate the developmental origin of tumor-induced ADAM12+ MSCs, we performed lineage tracing of ADAM12+ cells from development, because ADAM12 is expressed during organ morphogenesis." (PMID 37798557, 2023). "As TGF-β expression is induced at early tumor stages, we started ablating Tgfbr2 in ADAM12+ cells by removing doxycycline at the initiation of tumorigenesis." (PMID 37798557, 2023). "Peduto and colleagues report a role for ADAM12+ mesenchymal stromal cells at the tumor margins and their interaction with immune cells to promote a permissive ‘protumor’ environment." (PMID 37798557, 2023). "It is worth noting that ADAM12, a secreted protein that can be detected in both blood and body fluids, is a good potential tumor biomarker." (PMID 36717944, 2023). "ADAM12 overexpression was shown to promote tumor growth and metastasis, while its knockdown had a reverse effect, thus inhibiting cell proliferation, migration and invasion." (PMID 37370817, 2023). "Mechanistically, ADAM12 regulates cancer cell proliferation and survival, either through its ability to shed growth factors and adhesion molecules from the surface of tumor cells or via its interaction with cell surface molecules such as integrins." (PMID 37495855, 2023). "Tumors were better perfused, overall confirming a similar role for ADAM12+ cells in this tumor model." (PMID 37798557, 2023). "TCGA database revealed that ADAM12 was significantly upregulated in ccRCC tissues and was positively correlated with T stage and tumor stage in ccRCC patients (p < 0.001)." (PMID 36717944, 2023). "Overall, these data show that ADAM12+ MSCs are induced at early tumor stages and polarize tumor macrophages toward an immunosuppressive and proangiogenic phenotype by promoting efferocytosis." (PMID 37798557, 2023). "A disintegrin and metalloproteinase 12 (ADAM12) is aberrantly expressed in various cancers and plays an important role in tumor progression." (PMID 36717944, 2023). "ADAM12+ MSCs are restricted to the tumor margin, further suggesting that they spatially coordinate with TAMs to relay signals from the margin." (PMID 37798557, 2023). "Our data are consistent with a protumor effect of cytostasis, mediated by TGF-β, on perivascular MSCs, as selective depletion of ADAM12+ MSCs or conditional ablation of Tgfbr2 in ADAM12+ MSCs was sufficient to inhibit tumor growth." (PMID 37798557, 2023). "Consistent with inhibition of macrophage polarization toward proangiogenic TAMs, depletion of ADAM12+ MSCs induced normalization of the tumor vasculature." (PMID 37798557, 2023). "After treating with doxycycline 10-week-old TRAMP x ADAM12-tTA-CreYFP mice that had been fate mapped from week 4, we analyzed the fate of ADAM12+ cells induced specifically at early tumor stages." (PMID 37798557, 2023). "CS was reported to induce ADAM12+ CTLA4+ Tregs (a unique subset of tumor-specific activated Tregs) which interact with exhausted T cells in the tumor immune environment of lung cancer." (PMID 37324952, 2023). "Altogether, our data show that depletion of tumor-induced slow-cycling PDGFRα+ MSCs through ADAM12 restores antitumor immunity." (PMID 37798557, 2023). "We observed significant inhibition of tumor growth, as well as increased infiltration of T cells, in ADAM12-tTA-CreTgfbr2 mice compared with WT littermate mice, showing that TGFBR2 is required for the pro-tumorigenic role of ADAM12+ cells." (PMID 37798557, 2023). "Macrophages isolated from MO5 tumors growing in ADAM12-tTA-CreTgfbr2 mice expressed lower levels of Vegfa, a major inducer of leaky vessels, and tumor vessels had improved pericyte coverage, consistent with blood vessel normalization." (PMID 37798557, 2023). "In larger tumors, ADAM12+ cells remained localized at the tumor margin, and a majority (>80%) were in close proximity to macrophages with phosphorylated AXL (AXL-P+), a receptor that is essential for efferocytosis, and were distant from T cells." (PMID 37798557, 2023).
tumor (continued). "In the xenograft tumor model, ADAM12 knockdown significantly repressed the volume and weight of the tumors, whereas ADAM12 overexpression had the opposite effect." (PMID 36717944, 2023). "For 227 (97%) of patients with serum ADAM12 measurements information on primary tumor location was available." (PMID 35413826, 2022). "Together, these data indicate that ADAM12 is specific to the CAF component of the tumor stroma in CRC." (PMID 35413826, 2022). "Treatment strategies which target the tumor stroma or are dependent on stroma-related properties will most probably be the best candidates for the predictive power of ADAM12." (PMID 35413826, 2022). "In agreement, we found that ADAM12 expression was high in CRC bulk tumor tissue but low in pure epithelial cell populations." (PMID 35413826, 2022). "Using IHC and q-RT-PCR, the transcription and expression pattern of ADAM12 in GC cells and the corresponding non-tumour tissue as well as in GC cell lines were examined." (PMID 35565436, 2022). "Univariate regression analysis revealed that ADAM12 mRNA expression was correlated with tumor grade, T stage, and M stage, as well as overall survival." (PMID 35094638, 2022). "The results showed that ADAM12 expression was increased in ccRCC tissues and cells and significantly correlated with patient gender, Tumor stage, Metastasis stage, Node stage, and clinical grade." (PMID 35094638, 2022). "The tumor grade and T, M, and N stages tended to be more posterior, which was also consistent with the results of ADAM12 in other tumors studied by other authors, indicating that ADAM12 can be a potential biomarker for ccRCC." (PMID 35094638, 2022). "In the AMC-AJCCII-90 bulk tumor RNA expression, ADAM12 gene expression was found to be high in CMS4." (PMID 35413826, 2022). "On the basis of TCGA data, the expression differences in ADAM12 gene mRNA in different tumour tissues and normal tissues were analysed by Wilcoxon signed-rank test." (PMID 35459884, 2022). "Consistently, analysis in the three GEO datasets yielded a higher expression of ADAM12 in the tumor group." (PMID 35094638, 2022). "The results strongly suggested that ADAM12 regulated various immune molecules in the tumor microenvironment of CRC through many pathways, thereby affecting immune cell infiltration." (PMID 34604068, 2021). "The difference and correlation between ADAM12 expression and tumor-infiltrating immune cells showed that 12 tumor-infiltrating immune cells were significantly correlated with ADAM12 expression." (PMID 34663825, 2021). "High expression of ADAM-15 and ADAM-12 were found in PC tissues and sera/urine of patients affected by PC with advanced pathological tumor stages with metastasis, respectively." (PMID 35011576, 2021). "The effect of ADAM12 on tumor cell behavior was assessed in CRC cell lines, CRC tissues, and a mouse xenograft model." (PMID 33923541, 2021). "The ADAM12-mediated cleavage of ephrin-A1 induces vascular leakage in the lungs, resulting in an enhancement of tumor cell intravasation defined as metastasis." (PMID 33804570, 2021). "The tumor area, volume, and weight for the ADAM12-pGFP-C-shLenti-transfected group were significantly lower compared to the scrambled pGFP-C-shLenti-transfected group." (PMID 33923541, 2021). "Both ADAM12 and matrix metalloproteinase proteins are members of the protease family and promote tumor cell invasion by regulating cell–cell or cell–extracellular matrix interactions." (PMID 34604068, 2021). "The tumor area, volume, and weight in the ADAM12-pGFP-C-shLenti-transfected mice were significantly reduced compared to those in the scrambled pGFP-C-shLenti-transfected mice." (PMID 33923541, 2021). "ADAM12 has also been shown to regulate tumor progression in mouse tumor models, either by enhancing resistance to tumor cell apoptosis, by increasing tumor cell proliferation and invasion, or by promoting epithelial-to-mesenchymal transition." (PMID 33923541, 2021).
tumor (continued). "On the contrary, editing within miR-589-3p retargets the miRNA to the ADAM Metallopeptidase Domain 12 (ADAM12) to contrast the progression of the tumor." (PMID 34282776, 2021). "Other studies have shown that ADAM12 is associated with the EGFR signaling pathway and mediates tumor progression through interactions with other factors." (PMID 34604068, 2021). "In a mouse xenograft model, tumor area, volume, and weight were significantly greater for the ADAM12 overexpression group and significantly lower for the ADAM12 knockdown group." (PMID 33923541, 2021). "The tumor area, volume, and weight in the ADAM12-pcDNA6-myc-transfected mice were significantly greater than those of the empty-pcDNA6-myc-transfected mice." (PMID 33923541, 2021). "ADAM12 is highly expressed in tissues characterised by exaggerate growth, such as human placenta and tumours." (PMID 33507683, 2021). "Differences in ADAM12 expression between tumor and normal tissues from patients with different cancers were analyzed using the Oncomine database." (PMID 34604068, 2021). "The authors reported that cellular immunostainings for ADAM12 and ADAM12 mRNA decreased with a higher histological grade of the tumor." (PMID 34638718, 2021). "To elucidate the underlying mechanisms leading to these results, we analyzed the effect of ADAM12 on the stimulation of multiple intracellular signaling pathways regulating tumor cell survival." (PMID 33923541, 2021). "Functional correlation between NCAM, HNK-1, collagen, ADAM12 and β1-integrin adhesion and also neurite outgrowth in brain-tumor cells are key interactions in various tissues and can in principle be triggered by the use of certain heavy metal ions." (PMID 34869589, 2021). "After 37 days, the tumor area, volume, and weight of the mice in the ADAM12-pcDNA6-myc-transfected group were significantly greater than those of the mice in the empty-pcDNA6-myc-transfected group." (PMID 33923541, 2021). "Increased expression of many Adamalysins including ADAM8, ADAM9, ADAM10, ADAM12 and ADAM17 was reported in HCC and associated with tumor progression." (PMID 33805340, 2021). "In three different studies, it was shown that ADAM12 controlled tumour progression in gene modified mice models." (PMID 33507683, 2021). "During tumour progression, growth factors are liberated through the activity of MMPs such as ADAM-12, a disintegrin responsible for ECM proteolysis." (PMID 32386517, 2020). "ADAM12 overexpression has been reported in many tumours, especially in BC, where it has been proposed to make an important contribution in carcinogenesis." (PMID 32019179, 2020). "We further analysed the methylation status of VWCE, TSPAN9 and ADAM12 genes in 45 adjacent-to-tumour tissues." (PMID 32019179, 2020). "ADAM-12 exhibits catalytic activity by cleaving certain ligands that are biologically important for tumour growth, such as tumour necrosis factor-alpha (TNF-α), epidermal growth factor (EGF), and transforming growth factor-alpha (TGF-α)." (PMID 32386517, 2020). "Future analysis also will need to assess ADAM12 methylation status in haematopoietic cells as intrasample control since, besides tumour, those cells are also a source of cfDNA." (PMID 32019179, 2020). "Multiple studies have shown that ADAM12 is contributed to tumor progression and metastasis in COAD, HNSC, and LUAD." (PMID 33324676, 2020). "For instance, our discovery of ADAM12 hypomethylation in tumour and in cfDNA from TNBC patients, although in a very small series, would support the proof of concept to carry out these analyses in larger cohorts." (PMID 32019179, 2020). "There was high-intensity staining of ADAM-12 in the nucleus of tumour parenchyma cells, whereas the stroma showed low-intensity staining." (PMID 32386517, 2020). "ADAM-12 is a zinc-dependent metalloprotease related to the pathogenesis of some neoplasms and invadopodia formation under hypoxic conditions." (PMID 31319505, 2019).
tumor (continued). "It is believed that ADAM-12 is capable of stimulating tumor growth by cleaving and releasing certain ligands that are biologically active, such as the heparin-bound epidermal growth factor (HBEGF)." (PMID 31319505, 2019). "The expression of ADAM12 has been shown to localize to tumor vasculature and exert regulatory control over local angiogenesis." (PMID 31882975, 2019). "ADAM12 contributes to tumor progression and metastasis by promoting tumor cell proliferation, migration, invasion, and apoptosis resistance." (PMID 30746900, 2019). "We demonstrated ADAM12 and IL-6 levels to be unrelated to tumor burden, solidifying the value of these markers in assessing the activation status of stroma, as opposed to merely reflecting total tumor burden." (PMID 31207904, 2019). "Altogether, these data agree with and extend our mechanistic data obtained in vitro, arguing that KAT2A negatively regulate ADAM12 expression in several prevalent human tumor types." (PMID 30753595, 2019). "It thus appears that activated stroma, as revealed by high serum ADAM12 levels, contributes to poor disease outcome when the tumor is at a resectable stage." (PMID 30442938, 2018). "ADAM12 expression correlates with tumor stage in breast and bladder cancer, and is prognostic in small cell lung cancer." (PMID 30442938, 2018). "Collectively, these results suggested that ADAM12 knockdown decreased both tumor initiation and tumor growth in mice in vivo." (PMID 28148288, 2017). "To examine the role of ADAM12 in tumor initiation in vivo, we performed limiting dilution transplantation experiments." (PMID 28148288, 2017). "We next analyzed the effect of ADAM12 silencing using a xenograft tumor growth model and 5-FU treatment." (PMID 28852196, 2017). "In OSCC, increased expression of ADAM12 mRNA and protein has been observed and correlated with primary tumor size and tumor stage." (PMID 27128408, 2016). "During the last decade, ADAM12 emerged as the most strongly functional ADAM in human tumor development." (PMID 26407179, 2015). "ADAM12 has been shown to regulate tumor progression in mouse models either by increasing tumor cell resistance to apoptosis, by providing stromal support or by inducing cell proliferation." (PMID 26407179, 2015). "The expression of these proteins correlated with tumor areas in which cells had more “active” appearing nuclear features, and high expression of ADAM12, FAP, and WISP1, and low expression of SOX11, correlated with worse clinical outcome." (PMID 24402778, 2014). "We have taken advantage of these existing quantitative approaches to develop our own models, which we have applied to the study of the role of the ADAM12 tumor biomarker and of the TIF1γ tumor suppressor." (PMID 24618419, 2014). "The highly metastatic animal model confirmed that the expression of ADAM-12 was increased when tumor invasion and metastasis was enhanced, suggesting that ADAM-12 plays an important role in SCLC progression, invasion and metastasis." (PMID 24465799, 2014). "We selected ADAM12 for further analysis because it was one of the few genes that we found to be overexpressed in pancreatic CAFs and known to function in tumor-stromal cell interactions." (PMID 22984426, 2012). "Amounts of ADAM-12 mRNA transcripts were increased in tumour tissues as compared to the corresponding controls." (PMID 16495931, 2006). "ADAM12 was also present in the stromal ECM surrounding some of the ADAM12 positive tumours." (PMID 40998421, 2025). "This suggests that ADAM12 may potentially play a role in promoting immunosuppression within the tumor microenvironment (TME) of TNBC." (PMID 38317965, 2024). "Thus, we found increased deposits of collagen type 5 in the stroma of nude mice tumors of the human tumor cell line MCF7 expressing ADAM12—mimicking the desmoplastic response seen in human cancer." (PMID 38892056, 2024).